KAT6B (lysine acetyltransferase 6B)
Description:
Histone acetyltransferase which may be involved in both positive and negative regulation of transcription. Required for RUNX2-dependent transcriptional activation. May be involved in cerebral cortex development. Component of the MOZ/MORF complex which has a histone H3 acetyltransferase activity.
Synonyms: MORF; MOZ2; MYST4; querkopf; qkf; GTPTS; ZC2HC6B
Tractability: Small molecule: a high-quality ligand is known. PROTAC: UniProt records ubiquitination sites on it; ubiquitination databases record sites on it; a small molecule that binds it is known.
Target class: Enzyme
Chemical probes: PF-9363 (high quality), WM 1119 (high quality)
Gene: Protein-coding gene on chromosome 10 (74,824,912 to 75,032,631, forward strand). Ensembl gene ENSG00000156650.
Subcellular location: Nucleus
Subcellular location (Human Protein Atlas): Nucleoplasm; Mitotic chromosome; Nuclear bodies; Nucleoli
Pathways (Reactome):
Chromatin organization: HATs acetylate histones
Gene Ontology:
Molecular function: histone acetyltransferase activity; histone H3K14 acetyltransferase activity; protein binding; protein-lysine-acetyltransferase activity; transcription coactivator activity; chromatin binding; histone H3 acetyltransferase activity; transcription coregulator activity; DNA binding; protein-containing complex binding
Biological process: negative regulation of DNA-templated transcription; positive regulation of DNA-templated transcription; regulation of DNA-templated transcription; nucleosome assembly; regulation of developmental process; regulation of hemopoiesis; regulation of transcription by RNA polymerase II; positive regulation of transcription by RNA polymerase II
Cellular component: MOZ/MORF histone acetyltransferase complex; nucleus; nucleoplasm; nucleosome
Genetic constraint (gnomAD): Loss-of-function variants: 10 observed, 173.91 expected, observed/expected ratio (o/e) 0.0575, 90% interval 0.034 to 0.098. The upper end of that interval is the gene's LOEUF score, 0.098, which puts it in group 1 of 6, group 1 being the genes least tolerant of losing a copy. Missense variants: 1,884 observed, 2,562 expected, observed/expected ratio (o/e) 0.74, 90% interval 0.71 to 0.76. Synonymous variants: 831 observed, 942.92 expected, observed/expected ratio (o/e) 0.88, 90% interval 0.83 to 0.93.
Gene-disease validity (ClinGen):
ClinGen rates the evidence that KAT6B causes each of these diseases.
KAT6B-related multiple congenital anomalies syndrome (autosomal dominant): Definitive.
RASopathy (autosomal dominant): Disputed. Developmental syndromes caused by germline mutations (or in rare cases by somatic mosaicism) in genes that alter the Ras subfamily and mitogen-activated protein kinases that control signal transduction.
Homologues: Orthologues: chimpanzee KAT6B (99% identical), macaque KAT6B (99% identical), pig KAT6B (95% identical), dog KAT6B (95% identical), rabbit KAT6B (94% identical), mouse Kat6b (90% identical), rat Kat6b (88% identical), guinea pig KAT6B (79% identical), zebrafish kat6b (36% identical), Drosophila melanogaster tth (3% identical), Drosophila melanogaster d4 (3% identical), Caenorhabditis elegans dpff-1 (2% identical). Paralogues in human: KAT6A (51% identical), KAT7 (12% identical), RSF1 (10% identical), KAT5 (10% identical), KAT8 (9% identical), PHF10 (5% identical), DPF2 (4% identical), DPF3 (4% identical), DPF1 (4% identical).
Diseases named in the same sentence as KAT6B in open-access papers:
KAT6B is named in the same sentence as 85 diseases in open-access papers, as found by Europe PMC text mining. Sharing a sentence is not in itself a finding about the gene and the disease. The quoted sentences say what the papers report.
genitopatellar syndrome (16 papers, 2014 to 2025). "For example, different types of pathogenic variants within the lysine acetyltransferase 6B (KAT6B) gene are linked to two distinct syndromes, namely genitopatellar syndrome (GPS) or Say-Barber-Biesecker-Yong-Simpson syndrome (SBBYSS)." (PMID 39135741, 2024). "Heterozygous mutations of KAT6B in humans cause Genitopatellar syndrome (GPS), a developmental disorder with intellectual disability." (PMID 36768434, 2023). "The KAT6B gene mutation also causes Genitopatellar syndrome, which is mainly characterized by flexion contractures of the hip and knee joints, and ankle foot deformities." (PMID 32448279, 2020). "Heterozygous pathogenic variants in the KAT6B gene, which encodes lysine acetyltransferase 6B, have been identified in patients with congenital rare disorders, including genitopatellar syndrome and Say-Barber-Biesecker-Young-Simpson syndrome." (PMID 31871732, 2019). "Mutations of Kat6B have been identified in patients with Say-Barber-Biesecker syndrome and with genitopatellar syndrome." (PMID 29977151, 2018). "Recently, constitutional mutations in KAT6B were found to cause Genitopatellar syndrome (GPS) and the Say-Barber-Biesecker variant of Ohdo syndrome (SBBYSS)." (PMID 25621995, 2015). "In humans, KAT6B has been associated with Ohdo syndrome for which symptoms include skeletal, facial, cardiac and dental abnormalities and with genitopatellar syndrome, a skeletal dysplasia." (PMID 24884971, 2014). "Heterozygous de novo mutations in the KAT6B gene, which encodes the histone acetyltransferase, can cause two syndromes with mental retardation and congenital abnormalities, known as Genitopatellar syndrome (GPS; OMIM #606170) and Say–Barber–Biesecker–Young–Simpson syndrome (SBBYSS, OMIM #603736)." (PMID 38178270, 2024). "Also, KAT6B protein has been identified in different diseases such as genitopatellar syndrome, ohdo syndrome, Sbbyss variant, monocytic leukemia, and blepharophimosis." (PMID 38178270, 2024). "Genitopatellar syndrome is caused by a heterozygous mutation in the KAT6B gene and is characterized by patellar hypoplasia or agenesis, flexion contractures of the hips and knees, urogenital anomalies, developmental delay, hypotonia, and facial anomalies, including low-set ears and thin upper lip." (PMID 35844343, 2022). "Genitopatellar syndrome (GPS) and Say-Barber-Biesecker-Young-Simpson syndrome (SBBYSS) are extremely rare genetic disorders stemming from mutations in the lysine acetyltransferase 6B (KAT6B) gene." (PMID 39445296, 2024). "Genitopatellar syndrome (GPS) and Say-Barber-Biesecker-Young-Simpson syndrome (SBBYSS) are rare genetic disorders linked to mutations in the Lysine Acetyltransferase 6B (KAT6B) gene, affecting histone acetylation regulation and developmental processes." (PMID 39445296, 2024). "Heterozygous mutations in lysine acetyltransferase 6B (KAT6B, also known as MYST4) are associated with both genitopatellar syndrome (GPS) and Say-Barber-Biesecker variant of Ohdo syndrome." (PMID 25750614, 2014). "Heterozygous mutations in the MYST family histone lysine acetyltransferase gene, KAT6B (MYST4/QKF/MORF) cause the Say-Barber-Biesecker-Young-Simpson variant of Ohdo syndrome, Genitopatellar syndrome, and similar disorders, defined by a global development delay and cognitive impairment." (PMID 39537341, 2025).
breast carcinoma (11 papers, 2018 to 2025). "To elucidate the biological impact and mechanism of KAT6B::ADK in HR+/HER2‒ breast cancer progression, we initially tested the presence of KAT6B::ADK fusion genes in HR+/HER2‒ cell lines." (PMID 41213951, 2025). "Through integrative bioinformatics analysis and functional validation, we identified a novel KAT6B::ADK fusion as a promoter of breast cancer metastasis and endocrine therapy resistance." (PMID 41213951, 2025). "KAT6A and its paralog KAT6B have emerged as druggable targets for the treatment of malignancies, especially for breast cancer." (PMID 41357671, 2025). "Further microarray analyses following KAT6B knockdown revealed a reduction in the expression of a series of genes associated with tumor growth and invasiveness, which indicates the oncogenic impact of KAT6B in breast cancer." (PMID 41357671, 2025). "KAT6B has been found to play an important role in ERα regulation and contribute to breast cancer cell proliferation." (PMID 40427520, 2025). "A study showed that KAT6B knockdown in breast cancer cell lines decreased cellular proliferation and migration of tumor cells and prompted G2/M cell cycle arrest." (PMID 41357671, 2025). "An orally bioavailable KAT6A and 6B inhibitor that selectively inhibits the catalytic activity of KAT6A and KAT6B was recently shown to elicit on-target antitumor activity in vivo in ER+ breast cancer and other cancer types in preclinical studies." (PMID 38824244, 2024). "Inhibition of histone lysine acetyltransferases (KATs) KAT6A and KAT6B has shown antitumor activity in estrogen receptor-positive (ER+) breast cancer preclinical models." (PMID 38824244, 2024). "Whole exome sequencing (WES) detected multiple somatic variants in CTCs; some were in chromatin modeling factors KAT6B, KMT2D and KDM6A genes which are frequently mutated in breast cancer." (PMID 31003475, 2019). "Given our previous observations linking ADK fusion genes positivity to shorter survival in HR+/HER2‒ breast cancer patients, we hypothesized that KAT6B::ADK may contribute to endocrine therapy resistance." (PMID 41213951, 2025). "Data on its homolog, KAT6B, in breast cancer are relatively limited." (PMID 41357671, 2025). "KAT6A and KAT6B represent attractive epigenetic targets in the context of breast cancer biology." (PMID 41357671, 2025). "We next investigated the mechanism by which KAT6B::ADK activates kinase activity, hence promoting breast cancer cell migration and endocrine therapy resistance." (PMID 41213951, 2025). "To elucidate the intricate roles of ADK fusion genes in HR+/HER2‒ breast cancer, we identified several distinct fusion events involving ADK with 6 different partner genes: PCDH15, SEC24C, KAT6B, RSU1, NARS2, and LRMDA." (PMID 41213951, 2025). "Based on recently released preclinical data, the OP compounds, which potently inhibit both KAT6A and KAT6B, exhibit robust antitumor efficacy in ER+/HER2− breast cancer." (PMID 41357671, 2025). "What is worth mentioning, OP‐2, along with other OP compounds, exhibited potentiated selectivity against KAT6B (as evidenced by biochemical assays), which differentiates it from other KAT6 inhibitors being investigated in the context of breast cancer." (PMID 41357671, 2025). "Specifically, the most prevalent kinase fusion genes differed by subtype: MED1::CDK12 in HER2+ breast cancer, PTK2::AGO2 in TNBC, and KAT6B::ADK in HR+/HER2‒ breast cancer." (PMID 41213951, 2025). "Collectively, these findings underscore the role of KAT6B::ADK in enhancing the migratory and metastatic potential of HR+/HER2‒ breast cancer cells." (PMID 41213951, 2025). "Overall, KAT6A and KAT6B are attractive and desirable epigenetic targets for therapeutic leverage in human disease, particularly in ER+/HER2− breast cancer." (PMID 41357671, 2025).
breast carcinoma (continued). "Recent progress in drug discovery has led to the development of dual KAT6A and KAT6B inhibitors with potent antitumor efficacy and selectivity in both preclinical and clinical settings, supporting KAT6 as a druggable, promising target for the treatment of cancers, particularly breast cancers." (PMID 41357671, 2025).
acute myeloid leukemia (10 papers, 2007 to 2025). Acute myeloid leukemia (AML) is a group of neoplasms arising from precursor cells committed to the myeloid cell-line differentiation. "Several developmental disorders are caused by distinct mutations of KAT6B, and acute myeloid leukemia may be caused by a chromosomal aberration involving KAT6B gene." (PMID 34100716, 2021). "Molecular dysregulation of KAT6A and KAT6B has been observed in various tumor diseases, including solid tumors of the breast, lung, and ovary, as well as hematological tumors such as acute myeloid leukemia (AML)." (PMID 41357671, 2025). "Although KAT6B rearrangements have been reported in leiomyomas, rare examples of uterine leiomyosarcoma and acute myeloid leukemia, fusions involving KANSL1 are rare." (PMID 31027501, 2019). "In a form of acute myeloid leukemia, there is a translocation of the N-terminal portion of Kat6b in frame with CBP." (PMID 29977151, 2018). "Interestingly, MORF/MYST4 (KAT6B) is also involved in acute myeloid leukemia and the myelodysplastic syndrome with fusion to the CREB-binding protein (CBP) instead of p300, similar to that exhibited by MYST3/KAT6A." (PMID 33532133, 2021). "Translocations involving KAT6A (and KAT6B) is are identified in acute myeloid leukemia." (PMID 32877461, 2020).
Intellectual disability (10 papers, 2015 to 2025). "An example of SNVs found in this study as a VOUS is a heterozygous variant c.5675C > T in gene KAT6B found in a male patient diagnosed with developmental delay and intellectual disability." (PMID 36937954, 2023). "The two syndromes share features such as intellectual disability but also have their own particular symptoms, which seem to be dependent on the location of KAT6B mutations." (PMID 36077605, 2022). "Intellectual disability was universally present in individuals with variants in ZC4H2 (5/5), DYNC1H1 (4/4), TOR1A (2/2), KAT6B (1/1), GLDN (1/1), and GPC3 (1/1), signifying a strong association between these genes and cognitive deficits." (PMID 40443119, 2025). "SBBYSS results from heterozygous mutations in the KAT6B (MYST4/MORF/QFK) gene and is characterized by intellectual disability and autism-like behaviors." (PMID 38557491, 2024).
leukemia (8 papers, 2007 to 2023). A malignant (clonal) hematologic disorder, involving hematopoietic stem cells and characterized by the presence of primitive or atypical myeloid or lymphoid cells in the bone marrow and the blood. "Related to human disease, BRPF1/KAT6A/KAT6B mutations have all been identified as the cause of neurodevelopmental disorders, leukemia and other types of cancer." (PMID 36077605, 2022). "The human KAT6A and KAT6B genes mutated recurrently in leukemia, nonhematologic malignancies, and multiple developmental disorders." (PMID 37365518, 2023). "KAT6A and KAT6B were originally identified as genes rearranged in leukemia." (PMID 36077605, 2022). "KAT6B has been shown to be transcriptional coregulator that physically and functionally interacts with the Runt-related transcription factor 1 (RUNX1), a recurrent leukemia-associated target, and the nuclear receptor peroxisome proliferator-activated receptor-α (PPARα) to exert its role." (PMID 30041677, 2018).
leiomyoma (7 papers, 2015 to 2025). A well-circumscribed benign smooth muscle neoplasm characterized by the presence of spindle cells with cigar-shaped nuclei, interlacing fascicles, and a whorled pattern. "Six of the tumors were originally diagnosed as LG-ESS, one as leiomyoma, one as leiomyosarcoma, and the last case (in which molecular testing was a part of the diagnostic work-up) as a sarcoma with the KAT6B::KANSL1 fusion." (PMID 39627614, 2025). "Six of those had been originally diagnosed as LG-ESS, one as leiomyoma, one as leiomyosarcoma, and the remaining case as sarcoma with the KAT6B/A::KANSL1 fusion." (PMID 39627614, 2025). "Sarcomas with KAT6B/A::KANSL1 fusion were first described in one retroperitoneal and one uterine tumor originally diagnosed as leiomyoma, followed shortly after by a tumor initially diagnosed as uterine leiomyosarcoma." (PMID 39627614, 2025). "Additionally, three cases of smooth muscle tumors with KAT6B::KANSL1 fusion were described in the literature, two of which were diagnosed as leiomyomas and one as a leiomyosarcoma." (PMID 39627614, 2025). "Our case is the first to identify a KAT6B-KANSL1 gene fusion in a uterine leiomyoma, a finding that contributes to the evolving molecular landscape of leiomyomas that may allow for tailored therapeutic intervention or development of targeted therapy." (PMID 31027501, 2019).
glioma (6 papers, 2021 to 2026). A benign or malignant brain and spinal cord tumor that arises from glial cells (astrocytes, oligodendrocytes, ependymal cells). "Silencing KAT6B inhibits the enrichment of RNA polymerase II (RNA pol II) and histone H3 lysine 23 acetylation (H3K23ac) on the STAT3 promoter, while loss of STAT3 reverses KAT6B-induced inhibition of ferroptosis in glioma cells." (PMID 38072908, 2023). "We next tried to explore the underlying mechanism by which KAT6B regulated glioma." (PMID 35432536, 2022). "In glioma, KAT6B facilitates the acetylation of histone H3 at lysine 23 and the enrichment of RNA polymerase II at the STAT3 promoter in glioma cells, thereby promoting STAT3 expression and exerting an inhibitory effect on ferroptosis." (PMID 41513612, 2026). "For example, genetic silencing of a well-known histone acetyltransferase KAT6B reduces the enrichment of histone H3 lysine 23 acetylation on the STAT3 promoter region in glioma cell lines including U251 and LN229140." (PMID 41457120, 2025). "KAT6B reverses erastin-induced ferroptosis in glioma cells, indicating that KAT6B functions as an inhibitor of ferroptosis." (PMID 38072908, 2023). "Here, we identified that the expression of STAT3 was repressed by the KAT6B knockdown in glioma cells." (PMID 35432536, 2022). "The relationship of KAT6B-mediated apoptosis and ferroptosis and what is the main mechanism of KAT6B promoting glioma malignancy should be explored in future investigations." (PMID 35432536, 2022). "In this study, we uncovered the effect and the potential mechanism of KAT6B on ferroptosis in glioma cells." (PMID 35432536, 2022). "Our finding provides novel insights into the mechanism by which KAT6B regulates glioma progression by STAT3." (PMID 35432536, 2022). "We aimed to evaluate the effect of KAT6B on ferroptosis in glioma cells and explored the potential mechanisms." (PMID 35432536, 2022). "Here, we aimed to evaluate the effect of KAT6B on ferroptosis in glioma cells and explored the potential mechanisms." (PMID 35432536, 2022). "Meanwhile, the apoptosis of glioma cells was induced by the treatment of erastin, while the overexpression of KAT6B blocked the effect in the cells." (PMID 35432536, 2022). "Mechanically, we identified that the expression of STAT3 was repressed by the KAT6B knockdown in glioma cells." (PMID 35432536, 2022). "The viability of glioma cells was repressed by erastin, and the overexpression of KAT6B rescued the phenotype in the cells." (PMID 35432536, 2022). "Apart from a recent study suggesting a role in glioma progression and therapeutical resistance, little is known about the role of KAT6B in glioma, a lysine acetyltransferase of the MYST family with oncogenic or tumor suppressor properties depending on the cancer." (PMID 36766715, 2023). "We observed that the expression of KAT6B was enhanced in clinical glioma samples." (PMID 35432536, 2022). "In this study, overexpression of KAT6B could inhibit both apoptosis and ferroptosis of glioma cells." (PMID 35432536, 2022). "In this work, we studied the function of KAT6B in glioma cells." (PMID 35432536, 2022). "Meanwhile, STAT3 may be just one of the downstream factors of KAT6B-mediated glioma progression, and other mechanisms should be identified in future investigations." (PMID 35432536, 2022). "Depletion of STAT3 reversed KAT6B-regulated viability, apoptosis, and ferroptosis of glioma cells." (PMID 35432536, 2022). "Therefore, we concluded that KAT6B contributes to glioma progression by repressing ferroptosis via epigenetically inducing STAT3." (PMID 35432536, 2022). "Histone acetyltransferase KAT6B is involved in multiple cancer development but the function of KAT6B in glioma remains unclear." (PMID 35432536, 2022). "The KAT6B was able to enrich on the promoter of STAT3 in glioma cells." (PMID 35432536, 2022). "Thus, we concluded that KAT6B contributes to glioma progression by repressing ferroptosis via epigenetically inducing STAT3." (PMID 35432536, 2022).